MIR3179-3 (microRNA 3179-3)
Synonyms: hsa-mir-3179-3
Gene: MicroRNA gene on chromosome 16 (18,411,894 to 18,411,977, reverse strand). Ensembl gene ENSG00000266454.
Gene Ontology:
Biological process: miRNA-mediated post-transcriptional gene silencing
Cellular component: RISC complex
Homologues: Paralogues in human: MIR3179-1 (100% identical), MIR3179-2 (100% identical), MIR3179-4 (100% identical).